GPR27 (G protein-coupled receptor 27)
Description:
Orphan receptor. Possible candidate for amine-like G protein coupled receptor.
Synonyms: SREB1
Tractability: Small molecule: it belongs to a druggable protein family. Antibody: its Gene Ontology location is reachable by antibodies, with high confidence; UniProt places it where antibodies can reach, with medium confidence; UniProt predicts a signal peptide or a membrane-spanning region; the Human Protein Atlas places it where antibodies can reach. PROTAC: a small molecule that binds it is known.
Target class: Family A G protein-coupled receptor; Membrane receptor
Gene: Protein-coding gene on chromosome 3 (71,753,855 to 71,756,496, forward strand). Ensembl gene ENSG00000170837.
Subcellular location: Cell membrane
Subcellular location (Human Protein Atlas): Nucleoplasm; Actin filaments; Cytosol; Plasma membrane
Pathways (Reactome):
Signal Transduction: G alpha (s) signalling events
Gene Ontology:
Molecular function: G protein-coupled receptor activity
Biological process: signal transduction; G protein-coupled receptor signaling pathway
Cellular component: plasma membrane; membrane
Genetic constraint (gnomAD): Loss-of-function variants: 4 observed, 6.65 expected, observed/expected ratio (o/e) 0.6, 90% interval 0.29 to 1.36. That is too few expected variants to judge how well the gene tolerates losing a copy. Missense variants: 526 observed, 358.78 expected, observed/expected ratio (o/e) 1.47, 90% interval 1.36 to 1.58. Synonymous variants: 367 observed, 210.48 expected, observed/expected ratio (o/e) 1.74, 90% interval 1.6 to 1.9.
Homologues: Orthologues: chimpanzee GPR27 (100% identical), macaque GPR27 (99% identical), pig GPR27 (99% identical), dog GPR27 (98% identical), rat Gpr27 (97% identical), mouse Gpr27 (97% identical), zebrafish gpr27 (54% identical), tropical clawed frog gpr27 (51% identical). Paralogues in human: GPR173 (53% identical), GPR85 (52% identical).
Diseases named in the same sentence as GPR27 in open-access papers:
GPR27 is named in the same sentence as 19 diseases in open-access papers, as found by Europe PMC text mining. Sharing a sentence is not in itself a finding about the gene and the disease. The quoted sentences say what the papers report.
diabetes (2 papers, 2012 to 2020). "While this previous work indicates that Gpr27 may represent a new therapeutic target for diabetes, Gpr27 remains uncharacterized in vivo." (PMID 32221326, 2020). "We propose that Gpr27 is a novel target for diabetes therapeutics." (PMID 22253604, 2012).
hepatocellular carcinoma (2 papers, 2023 to 2024). A malignant tumor that arises from hepatocytes. "Recent research has implied that GPR27 might play critical roles during cancer progression, particularly in hepatocellular carcinoma (HCC) and breast cancer." (PMID 38638156, 2024).
Insulin resistance (2 papers, 2015 to 2020). Increased resistance towards insulin, that is, diminished effectiveness of insulin in reducing blood glucose levels. "To confirm impaired glucose tolerance, we challenged the mice with increased insulin resistance by placing an independent cohort of Gpr27 knockout mice and wild type littermate controls on a high fat diet from 3 weeks to 12 weeks of age." (PMID 32221326, 2020). "The genes adiponectin receptor 1, sestrin 3, KCNJ15 and G-protein coupled receptor 27 have all been described to play a role in insulin resistance, decreased insulin secretion and impaired blood glucose homeostasis." (PMID 25768297, 2015).
autism (1 paper, 2023). Persistent deficits in social interaction and communication and interaction as well as a markedly restricted repertoire of activity and interest as well as repetitive patterns of behavior. "There is evidence reporting that GPR27 plays an important role in nervous system diseases such as schizophrenia and autism." (PMID 37273699, 2023).
gastric cancer (1 paper, 2023). A primary or metastatic malignant neoplasm involving the stomach. "Firstly, we systematically explored the mRNA expression, DNA methylation, gene mutation and TMB of GPR27 in GC, and validated the bioinformatics conclusion with clinical cohort data, but this study does not explain the mechanism of GPR27 in gastric cancer cell’s growth and metastasis." (PMID 37702614, 2023). "Correlation of GPR27 expression and survival in gastric cancer with different clinical metrics by Kaplan-Meier plotter." (PMID 37702614, 2023).
glioma (1 paper, 2024). A benign or malignant brain and spinal cord tumor that arises from glial cells (astrocytes, oligodendrocytes, ependymal cells). "We found that GPR27 expression level was closely associated with disease status of glioma." (PMID 38638156, 2024). "However, more research is needed to fully understand the mechanisms underlying the role of GPR27 in glioma development and progression, as well as the potential therapeutic implications of targeting GPR27." (PMID 38638156, 2024). "The results presented in this study suggest that GPR27 expression levels are closely correlated with the disease status of glioma patients." (PMID 38638156, 2024). "Further studies are needed to illustrate the signaling mechanism and clinical implications of GPR27 in gliomas." (PMID 38638156, 2024). "We also conducted cellular experiments to evaluate the functional role of GPR27 in glioma cell growth." (PMID 38638156, 2024). "This study sheds light on expression and clinical relevance of GPR27 in gliomas and provides evidence for its oncogenic role in glioma growth." (PMID 38638156, 2024). "Consistently, cellular experiments suggest that GPR27 plays a crucial role in the development and progression of glioma, as overexpressing GPR27 expression significantly inhibited the proliferation capacities of U87 and U251 cell lines." (PMID 38638156, 2024). "In the current study, we evaluated the expression and clinical significance of GPR27 in gliomas using data from The Cancer Genome Atlas (TCGA) datasets." (PMID 38638156, 2024). "RNA expression data from TCGA datasets suggested that GPR27 expression was closely correlated with disease status of glioma." (PMID 38638156, 2024). "Accordingly, lower GPR27 expression was observed in elder patients, higher-grade gliomas, as well as in the specimens with wild-type IDH status or non-codeletion of 1p/19q (all P < 0.001)." (PMID 38638156, 2024). "Importantly, our data, for the first time, showed that higher GPR27 expression was an independent benefit biomarker for glioma prognosis (hazard ratio 0.679, 95% CI [0.486–0.947], P = 0.023)." (PMID 38638156, 2024). "However, further research is needed to fully understand the role of GPR27 in gliomas and to explore its potential as a therapeutic target." (PMID 38638156, 2024). "Taken together, clinical data analyses suggest that GPR27 may serve as a useful prognostic biomarker for glioma and may have implications for the development of novel therapeutic strategies." (PMID 38638156, 2024). "Orginal data for GPR27 expression correlates with prognosis and tumor progression in gliomas." (PMID 38638156, 2024). "Our results indicate that GPR27 may function as a potential prognostic biomarker and therapeutic target in gliomas." (PMID 38638156, 2024). "Taken together, our data highlights the potential clinical significance of GPR27 in gliomas." (PMID 38638156, 2024). "Additionally, in silico analysis showed that lower GPR27 expression was correlated with higher death rates in glioma patients." (PMID 38638156, 2024). "Importantly, Kaplan–Meier survival analysis indicated that lower GPR27 expression was a significant independent predictor of poor overall survival in glioma patients." (PMID 38638156, 2024). "Here we aimed to explore the function and role of GPR27 in gliomas." (PMID 38638156, 2024). "In cellular experiments, we confirmed that GPR27 inhibited glioma cell growth." (PMID 38638156, 2024). "Furthermore, the identification of GPR27 as a potential therapeutic target for glioma treatment is of significant clinical relevance, as there is a dire need for novel therapeutic strategies for this devastating disease." (PMID 38638156, 2024). "Therefore, it is high likely that GPR27 may modulate glioma progression via distinct signaling pathways in different cancer types." (PMID 38638156, 2024).
glioma (continued). "Moreover, the identification of GPR27 as a potential therapeutic target could pave the way for the development of new drugs, which could offer a promising avenue for glioma treatment." (PMID 38638156, 2024). "Modulation of GPR27 expression may be a promising therapeutic approach for treating glioma." (PMID 38638156, 2024). "Nevertheless, the clinical potential and tumor-related role of GPR27 in glioma remain unknown." (PMID 38638156, 2024). "Additionally, lower GPR27 expression is associated with elder patients, higher-grade gliomas, and specimens with wild-type IDH status or non-codeletion of 1p/19q, and predicts worse prognosis." (PMID 38638156, 2024). "Based on the multivariate survival analysis, we also established a nomogram to help predict overall survival of glioma patients; the variables in the nomogram included patients’ age, gender, WHO grade, IDH status, 1p/19q co-deletion, and GPR27 expression level." (PMID 38638156, 2024). "The observed negative correlation between GPR27 and various immune cell types suggests that GPR27 may play a role in immune evasion by glioma cells, and further investigations into the mechanism underlying this association could help to develop effective immunotherapeutic strategies." (PMID 38638156, 2024).
liver cancer (1 paper, 2024). An epithelial or non-epithelial malignant neoplasm that arises from the liver. "The study highlights the importance of GPR27 in HCC, a type of liver cancer, and proposes that GPR27 may promote tumor progression by activating the MAPK/ERK pathway." (PMID 38638156, 2024).
osteoporosis (1 paper, 2025). A condition of reduced bone mass, with decreased cortical thickness and a decrease in the number and size of the trabeculae of cancellous bone (but normal chemical composition), resulting in increased fracture incidence. "Additionally, the mRNA relative expression of CIR1, GPR27, and PDE8A were reduced in the osteoporosis group, while NIF3L1 and VPS35 were increased." (PMID 40980812, 2025).
cancer (4 papers, 2023 to 2024). A tumor composed of atypical neoplastic, often pleomorphic cells that invade other tissues. "Abnormal expression of GPR27 has been observed in these cancers, and it has been recognized to contribute to tumor growth and angiogenesis." (PMID 38638156, 2024). "To determine the functional relationship between GPR27 CN loss and PD, we analyzed gene expression and CN data obtained from CCLE (cancer cell lines) as well as gene expression data obtained from the GTEx database (normal tissues)." (PMID 36869069, 2023). "Our findings highlight the significance of GPR27 in a variety of cancers, including GC, and provide clues for a better understanding of GPR27 from bioinformatics and clinically validated perspective." (PMID 37702614, 2023). "Firstly, we investigated GPR27 mRNA expression level in various human cancers through TIMER and Xena Shiny." (PMID 37702614, 2023). "Pan-cancer analysis revealed that GPR27 was abnormally expressed in most of malignant neoplasms, including GC." (PMID 37702614, 2023). "Overall, these findings provide important insights into the role of GPR27 in the modulation of the immune response in the tumor microenvironment and could have significant implications for the development of novel cancer immunotherapies." (PMID 38638156, 2024). "However, further study will be needed to fully understand the exact mechanisms by which GPR27 affects cancer development and to explore its potential as a treatment target for cancers." (PMID 38638156, 2024). "We observed that GPR27 mRNA exhibits low expression level in GC tissues, which was in line with other GPCR member genes in cancer." (PMID 37702614, 2023). "Given the crucial role that the tumor microenvironment plays in cancer progression, GPR27 could serve as a potential target for the development of novel cancer immunotherapies." (PMID 38638156, 2024).
tumor (4 papers, 2017 to 2024). "To examine the association between GPR27 and immune cells, we applied ImmuCellAI to investigate the levels of 24 types of tumor infiltrating immune cells in GC." (PMID 37702614, 2023). "Conversely, our findings indicate an inverse relationship between GPR27 and macrophage presence, suggesting that lower GPR27 levels could be associated with increased macrophage presence within the tumor environment." (PMID 38638156, 2024). "In our research, we firstly examined the expression profile of GPR27 in various human tumors and normal tissues, then measured the potential correlation between GPR27 mRNA expression and its methylation levels, and investigated its correlation with mutations and tumor mutational burden (TMB)." (PMID 37702614, 2023). "G protein-coupled receptor 27 (GPR27) is a member of the G protein-coupled receptor family and has been reported to be involved in various cellular processes, including tumor progression." (PMID 38638156, 2024). "Significant differences were observed in tumor stage (P=0.0016) and distant metastasis (P=0.0335) between low-GPR27 and high-GPR27 groups." (PMID 37702614, 2023). "By moduclating the expression of GPR27, it may be possible to adjust the immune response in the tumor microenvironment to promote an anti-tumor immune response." (PMID 38638156, 2024). "Given the observed positive link between GPR27 and pDC presence, it’s plausible that the interaction between GPR27 and pDC might contribute, at least in part, to GPR27′s tumor-fighting properties." (PMID 38638156, 2024). "Our results pointed out that GPR27 occupies a certain role in the adjustment of tumor immunity, and might be a novel target for immunotherapy in GC." (PMID 37702614, 2023). "Moreover, the other genes in the deletion, EIF4E3, RYBP, PROK2, and GPR27 all mediate activities that intersect with the PI3K pathway in a potentially tumor suppressive manner." (PMID 29057879, 2017). "We comprehensively investigated GPR27 mRNA expression, DNA methylation, TBM, prognostic significance, protein expression, and correlation with tumor-infiltrating immune cells based on multi-omic bioinformatics and clinical cohort data." (PMID 37702614, 2023).
infection (1 paper, 2012). The state of being infected such as from the introduction of a foreign agent such as serum, vaccine, antigenic substance or organism. "To define the mechanism of Gpr27 action, we measured transcript levels of selected regulators of the insulin promoter by RT-QPCR in MIN6 cells after Ad-shGpr27 infection." (PMID 22253604, 2012).
GPR27 also shares sentences with these, for which no sentence is quoted: breast carcinoma (1 paper); developmental delay (1); Hyperglycemia (1); Impaired glucose tolerance (1); ovarian carcinoma (1); sarcopenia (1); schizophrenia (1); steatosis (1).